MYL2 (myosin light chain 2)
Description:
Contractile protein that plays a role in heart development and function. Following phosphorylation, plays a role in cross-bridge cycling kinetics and cardiac muscle contraction by increasing myosin lever arm stiffness and promoting myosin head diffusion; as a consequence of the increase in maximum contraction force and calcium sensitivity of contraction force. These events altogether slow down myosin kinetics and prolong duty cycle resulting in accumulated myosins being cooperatively recruited to actin binding sites to sustain thin filament activation as a means to fine-tune myofilament calcium sensitivity to force (By similarity). During cardiogenesis plays an early role in cardiac contractility by promoting cardiac myofibril assembly (By similarity).
Synonyms: MLC-2; MLC-2v; MLC-2s/v; MLC2; CMH10; MFM12
Tractability: Small molecule: an approved drug acts on it; a structure with a bound ligand is known.
Gene: Protein-coding gene on chromosome 12 (110,909,996 to 111,052,434, reverse strand). Ensembl gene ENSG00000111245.
Subcellular location: Cytoplasm, myofibril, sarcomere, A band
Subcellular location (Human Protein Atlas): Microtubules
Pathways (Reactome):
Muscle contraction: Striated Muscle Contraction
Gene Ontology:
Molecular function: actin monomer binding; calcium ion binding; protein binding; structural constituent of muscle; myosin heavy chain binding
Biological process: negative regulation of cell growth; ventricular cardiac muscle tissue morphogenesis; actin filament-based movement; cardiac muscle contraction; cardiac myofibril assembly; heart contraction; heart development; muscle cell fate specification; positive regulation of the force of heart contraction; regulation of striated muscle contraction; regulation of the force of heart contraction
Cellular component: actin cytoskeleton; cardiac myofibril; cytoskeleton; cytoplasm; cytosol; muscle myosin complex; myofibril; myosin complex; sarcomere; A band
Genetic constraint (gnomAD): Loss-of-function variants: 19 observed, 24.1 expected, observed/expected ratio (o/e) 0.79, 90% interval 0.55 to 1.16. The upper end of that interval is the gene's LOEUF score, 1.16, which puts it in group 5 of 6, group 1 being the genes least tolerant of losing a copy. Missense variants: 180 observed, 226 expected, observed/expected ratio (o/e) 0.8, 90% interval 0.7 to 0.9. Synonymous variants: 78 observed, 80.34 expected, observed/expected ratio (o/e) 0.97, 90% interval 0.81 to 1.17.
Gene-disease validity (ClinGen):
ClinGen rates the evidence that MYL2 causes each of these diseases.
hypertrophic cardiomyopathy (autosomal dominant): Definitive. A condition in which the myocardium is hypertrophied without an obvious cause.
dilated cardiomyopathy (autosomal dominant): Limited. Cardiomyopathy which is characterized by dilation and contractile dysfunction of the left and right ventricles.
arrhythmogenic right ventricular cardiomyopathy (autosomal dominant): No Known Disease Relationship.
Homologues: Orthologues: chimpanzee MYL2 (99% identical), macaque MYL2 (98% identical), dog MYL2 (97% identical), guinea pig MYL2 (96% identical), mouse Myl2 (96% identical), pig MYL2 (96% identical), rat Myl2 (95% identical), zebrafish myl2a (90% identical), tropical clawed frog myl2 (89% identical), zebrafish myl2b (87% identical), rabbit MYL2 (83% identical), Caenorhabditis elegans mlc-1 (49% identical), and 1 more. Paralogues in human: MYL10 (81% identical), MYL11 (72% identical), MYL5 (66% identical), MYL7 (62% identical), MYL12A (58% identical), MYL12B (57% identical), MYL9 (57% identical).
Diseases named in the same sentence as MYL2 in open-access papers:
MYL2 is named in the same sentence as 61 diseases in open-access papers, as found by Europe PMC text mining. Sharing a sentence is not in itself a finding about the gene and the disease. The quoted sentences say what the papers report.
hypertrophic cardiomyopathy (26 papers, 2014 to 2025). "Mutations in MYL2 in man have been found to cause both dilated and hypertrophic obstructive cardiomyopathy." (PMID 38879012, 2024). "We report a novel frameshift variant in MYL2 that is associated with a severe form of infantile-onset hypertrophic cardiomyopathy." (PMID 32453731, 2020). "MYL2 encodes a regulator protein of ventricular myosin ATPase activity and a mutation in this gene is associated with hypertrophic cardiomyopathy phenotype." (PMID 27195777, 2016). "The MYL2 gene encodes the cardiac myosin light chain protein, and previous studies have shown that a mutation in this gene results in left heart chamber hypertrophic cardiomyopathy." (PMID 26161779, 2015). "The MYL2 A13T (rs104894363) variant located in the regulatory light chain of myosin was reported to be causal for a subtype of familial hypertrophic cardiomyopathy with onset of clinical symptoms around middle age." (PMID 25333069, 2014). "For instance, variants in the myosin regulatory light chain (MYL2) including c.52T > C (p.Phe18Leu) have been reported to cause familial hypertrophic cardiomyopathy." (PMID 24297257, 2014). "In a final example, the techniques to study the heart in fly were used to establish causality for variants in Myosin light chain 2 (MYL2) associated with hypertrophic cardiomyopathy of infantile onset and characterized by mitral valve dysplasia, resulting in infant death." (PMID 37123266, 2023). "For example, the three variants linked to multiple variables in the arrhythmia category (MYBPC3:c.3288G>A, MYBPC3:c.2308+18C>G and MYL2:c.132T>C) are in genes associated with hypertrophic cardiomyopathy (HCM), where arrhythmias are secondary to ventricular remodeling." (PMID 36008935, 2022). "Furthermore, persons carrying mutations in MYL-2, encoding slow cardiac myosin regulatory light chain 2, developed hypertrophic cardiomyopathy in the presence of hypertension or other risk factors for hypertrophy." (PMID 32854392, 2020). "The mutation in MYL2 was shown to be responsible for hypertrophic cardiomyopathy (HCM) in humans." (PMID 30699152, 2019). "MYL2 mutations are associated with heart failure and familial hypertrophic cardiomyopathy." (PMID 27234427, 2016). "In the cases of dilated cardiomyopathy, cardiac muscle contraction, and hypertrophic cardiomyopathy (B), seven downregulated proteins were enriched, including Myl2, Myl3, Myh7, Atp2a1, Tpm1, Tpm2, and Ttn." (PMID 39861068, 2024). "KEGG analysis revealed that TPM1 and MYL2 were involved in the hypertrophic cardiomyopathy (HCM) pathway." (PMID 33785854, 2021). "Meanwhile, in the hypertrophic cardiomyopathy pathway and adrenergic signaling in cardiomyocyte pathway, which are closely related to the occurrence of hypertrophic cardiomyopathy, myosin Light Chain 2 (Myl2) and myosin Light Chain 3 (Myl3) were the most significant proteins with lactylation." (PMID 40281739, 2025). "Notably, among these proteins, MYL2, ACTN1, MYLK, COL1A2, COL6A2, and COL6A3 have been associated with dilated cardiomyopathy and hypertrophic cardiomyopathy pathogenic processes in previous studies." (PMID 37649075, 2023). "KEGG pathway analysis on cardiac loop genes reveals enrichments for terms, such as dilated cardiomyopathy, vasopressin-regulated water reabsorption, and hypertrophic cardiomyopathy (the genes within these terms include: Adcy6, Aqp3, Creb3l4, Des, Itgb5, Itga9, Myl2, Myl3, and Stx4a)." (PMID 30697540, 2018). "To this end, we conducted gene enrichment analysis, and observed stronger enrichments of upregulated genes involved in hypertrophic cardiomyopathy (ADRA1A, TNNI3, MYL2) and cardiac muscle contraction (CACNA1C, CASQ2, CAMK2B)." (PMID 37084237, 2023). "The most significantly enriched was hypertrophic cardiomyopathy, involving 3 downregulated genes (DES, IL6, and MYL2)." (PMID 35634509, 2022).
hypertrophic cardiomyopathy (continued). "The results showed that genes (DES, MYH6, MYL2, MYL3, TPM1, TPM3, TPM4, and TTN) in MCODE 2 were significantly involved in dilated cardiomyopathy and hypertrophic cardiomyopathy (HCM)." (PMID 35645614, 2022). "Next, our KEGG analysis showed that transcripts up-regulated in the mutant cardiomyocytes were related to hypertrophic cardiomyopathy (ACTC1, MYL2, MYL3), Ca2+-dynamics regulatory pathway (ATP2B4, CACNA1C, CAMK2B, PLN), as well as cardiac-muscle contraction transcripts (ACTC1, MYH7, TNNI3, TNNT2)." (PMID 35784482, 2022). "Notably, tropomyosin 1 (TPM1), myosin light chain 2 (MYL2), myosin heavy chain 11 (MYH11) and other DEPs were involved in hypertrophic cardiomyopathy, dilated cardiomyopathy and other pathways." (PMID 33785854, 2021).
cardiomyopathy (23 papers, 2011 to 2026). A disease of the heart muscle or myocardium proper. "This work focuses on MYL1 while noting that biallelic MYL2 pathogenic variants cause a myopathy with early onset after birth, leading to progressive cardiomyopathy and early death in infants (OMIM #619424)." (PMID 40488356, 2025). "Tg-E143K and Tg-D94A models of RCM and DCM, respectively, have been instrumental in confirming the perception that the mutations identified in MYL3 and MYL2 genes cause cardiomyopathy with typical features of human disease observed in these mouse models." (PMID 37511838, 2023). "Our GO and KEGG analyses revealed that HECTD4 and MYL2 are associated with cardiomyopathy, suggesting that the connection between AKT1 and the ApoA1 level has a direct connection to CVDs." (PMID 36140721, 2022). "The functional analysis of our data for two new loci (HECTD4 and MYL2) shows that they are associated with cardiomyopathy, suggesting that the association between AKT1 and the ApoA1 level has a direct connection to CVDs." (PMID 36140721, 2022). "A report of recessive MYL2 pathogenic variants has been reported in a Dutch family, as well as in an Italian patient with skeletal muscle Fiber-type I hypotrophy along with cardiomyopathy, further adds to the variability in disease manifestation." (PMID 32453731, 2020). "We compared the stability of this variant to that of other cardiomyopathy associated MYL2 variants and found molecular differences that correlated with disease pathology." (PMID 32453731, 2020). "These functional testing results shed light on the molecular pathology of this novel MYL2-fs variant as well as reported compound heterozygous and homozygous recessive MYL2 variants leading to early-onset cardiomyopathy." (PMID 32453731, 2020). "Diseases associated with MYL2 include cardiomyopathy, familial hypertrophic, and congenital fiber-type disproportion." (PMID 31611909, 2019). "To date, about 16 single amino acid mutations in MYL2 have been linked to various forms of cardiomyopathy." (PMID 27378946, 2016). "Our previous research showed that the properties of both of these two functional sites (Ca2+-binding site and phosphorylation site) of the RLC can be significantly altered in the presence of cardiomyopathy-associated mutations in MYL2." (PMID 27378946, 2016). "Furthermore, GO and KEGG analyses revealed that HECTD4 and MYL2 are associated with cardiomyopathy, suggesting that the association between AKT1 and the ApoA1 level has a direct connection with CVDs." (PMID 36140721, 2022). "This contrasts with other dominant variants in MYL2 that are associated with cardiomyopathies." (PMID 32453731, 2020). "MYL2 [Ensembl:ENSCAFG00000008524] is involved in the development of the sarcomere and muscle contraction and has also been associated with cardiomyopathy of the heart ventricle." (PMID 21722374, 2011). "Pathogenic variants in MYL2, MYL3 and MYL4 genes cause various isolated cardiomyopathies." (PMID 40488356, 2025). "In April 2024, the ClinGen Cardiomyopathy Variant Curation Expert Panel (VCEP) adapted the ACMG/AMP criteria for eight of the sarcomeric genes (MYH7, MYBPC3, TNNI3, TNNT2, TPM1, ACTC1, MYL2, and MYL3), providing a refined framework for variant interpretation in these genes." (PMID 41357762, 2025). "However, 7 of them may be related to the processes associated with DCM since these candidate proteins were directly associated to other types of cardiomyopathies, such as HCM (e.g. MYL2 and MYL3)." (PMID 23940716, 2013). "Changes in the levels of myosin light chain 2 and myosin light chain 3 (MYL2 and MYL3) proteins upon isoproterenol treatment, observed in our study are consistent with the earlier observations of heart failure or cardiomyopathy." (PMID 23706090, 2013). "Although MYL2 and MYL3 have not been validated to be directly associated to DCM, their relationships with other cardiomyopathies have been mentioned in literature." (PMID 23940716, 2013).
cardiomyopathy (continued). "Additional cluster 3 proteins categorized to cardiomyopathy and sarcomeric proteins exposed to constant mechanical stress, including Desmin (DES), dystrophin muscular dystrophy (DMD); myosin binding protein C, cardiac (MYBPC3); myosin light polypeptide 2 (MYL2); Titin (TTN) and phospholamban (PLN)." (PMID 36681760, 2023). "Therefore, it was speculated that TPM1, MYL2 and MYH11 could be the targets of obesity-induced cardiomyopathy, thus providing a theoretical basis for future drug development." (PMID 33785854, 2021). "Secondly, the in-depth mechanism of TPM1, MYL2 and MYH11 protein changes in obese cardiomyopathy has not been studied." (PMID 33785854, 2021).
dilated cardiomyopathy (14 papers, 2013 to 2025). "Hypertrophic and dilated cardiomyopathy causing mutations have been detected mostly in genes of sarcomere proteins such as Mybpc2, Myh7, Tnnt2, Tnnc1, Tnni3, Tpm1, Ttn, Actc1, Myl2, and Myl3." (PMID 38981849, 2024). "It has been demonstrated that mutations in genes encoding cytoskeletal proteins, including tropomyosin 1 (TPM1) and myosin light chain 2 (MYL2), can cause dilated cardiomyopathy with impaired contractility and diastolic function." (PMID 33785854, 2021). "In dilated cardiomyopathy, the aspartate-to-alanine substitution atposition 94 in the regulatory light chain of myosin (RLC) encoded by the myosin regulatory light chain 2 (MYL2) gene results in anincreased number of SRX heads and a subsequent reduction in myocardial contractility." (PMID 39077080, 2023). "Necroptosis, neutrophil extracellular trap formation, cardiac muscle contraction, and dilated cardiomyopathy, among others, are some pathways affected by downregulated proteins such as Pgam5, Slc25a4, and H2ax as well as Myl2, Myl3, Atp2a1, and Tpm2." (PMID 41011134, 2025). "The impact of HCM mutations, as well as dilated cardiomyopathy (DCM) mutations can now be evaluated with this accurate high-resolution human β-cardiac IHM structure, including those affecting the MYL2 and MYL3 genes that code for the RLC and ELC proteins, respectively." (PMID 37258552, 2023). "For example, decreased MYL2 and MYH6 gene expression coincided with increased RYR2, HCN4, CORIN, NPPA, ERBB2, and MYH7 gene expression in hypertrophic and/or dilated cardiomyopathy." (PMID 32804947, 2020). "Among the remaining 19 DEGs, IGF1 (NO.17), MYL2 (No. 31), PCK1 (No. 33) and PRKACA (No. 39) were involved in the pmAF – related PPAR signaling pathways, focal adhesion and dilated cardiomyopathy." (PMID 24204599, 2013).
cardiac hypertrophy (13 papers, 2010 to 2025). "We also assessed LVH with activity changes of ventricular myosin light chain 2 (MLC2v) and Rho-associated kinase 1/2 (ROCK 1/2), two well-established markers of cardiac hypertrophy." (PMID 39804876, 2025). "Several genes, including NPPA (natriuretic peptide A), ACTC1 (alpha-cardiac actin), MYL2 (myosin regulatory light chain 2), and MYL7 (myosin regulatory light chain 7), have been previously implicated in cardiac hypertrophy." (PMID 34422789, 2021). "In this cohort, a female patient with mixed apical hypertrophy (25 mm) and fibrosis on the CMR was found to have a pathogenic variant in the myosin light-chain-2 gene, MYL2, along with two VUSs in the MYH7 gene, which may contribute to the apical phenotype." (PMID 40428316, 2025). "GH may regulate cardiac growth and metabolism by increasing protein synthesis (troponin I, myosin light chain-2, and actin), and cardiomyocyte size, increasing collagen synthesis and promoting cardiac hypertrophy." (PMID 29346331, 2018). "A marked reduction in MYL2 and MYL3 protein and mRNA levels was also observed in the hearts of rats with isoproterenol-induced cardiac hypertrophy." (PMID 33498641, 2021). "cardiac hypertrophy, cancer, cell death and survival with upregulation of proteins such as MYH7, MYL2, APOA1 and phospholamban (Table of Top enriched networks from core analysis of both H9c2 and GK overexpressed proteins S1 Table)." (PMID 34166385, 2021). "Leptin also significantly increased expression of α-skeletal actin and myosin light chain-2 (MLC-2), both upregulated in cardiac hypertrophy." (PMID 26064110, 2015).
heart failure (11 papers, 2013 to 2025). Inability of the heart to pump blood at an adequate rate to meet tissue metabolic requirements. "In patients with heart failure, the level of MYL2 is reduced, which is associated with the severity of myocardial disease." (PMID 33785854, 2021). "Conditional adult-onset Mylk3 knockout mice have drastically reduced MYL2 phosphorylation which precedes heart failure, whereas germ line ablation causes mice to develop DCM in adulthood, and perinatal ablation produces an intermediate phenotype." (PMID 32213617, 2020). "MYL2 and its phosphorylation levels in the heart of Mlck-deficient mice were decreased, which resulted in cardiac dysfunction, and rapidly progressed to heart failure, with the histological manifestations of myocardial tissue disorder, fibrosis, reduced contractility and cell death." (PMID 33785854, 2021). "While in ex vivo rat cardiac myocytes, the level of myosin light chain 2 mRNA increases upon treatment with phenylephrine; the mRNA for α-myosin heavy chain decreases in aged spontaneously hypertensive rats with heart failure." (PMID 31920643, 2019). "Down regulation of MYL2 was observed in human heart failure tissues and this data suggested that MYL2 may play a role in the development and progression of chronic heart failure." (PMID 23706090, 2013). "Therefore a change in MYL2 expression or phosphorylation might contribute to hypertrophy and over a longer time to heart failure development." (PMID 27234427, 2016).
Obesity (5 papers, 2016 to 2024). Accumulation of substantial excess body fat. "It was suggested that obesity may reduce the binding of myosin and actin, and the regulation of Ca2+ by reducing the expression of MYL2, thus causing myocardial contractility disorder, which is involved in the occurrence of obese cardiomyopathy." (PMID 33785854, 2021). "In the present study, the expression of MYL2 was decreased in mice with obesity induced by a high-fat diet." (PMID 33785854, 2021). "It is worth noting that the SNP rs12229654 at MYL2 and its related SNP rs671 at ALDH2 were associated with every obesity trait analyzed (WCadjBMI, WHRadjBMI, WCnoBMI, and WHRnoBMI), with larger effects observed in men." (PMID 26785701, 2016). "Claes et al27 reported a penetrance of 89% in biallelic MYL2 variant carriers or in heterozygous individuals suffering from hypertension or obesity versus 36% in MYL2 variant carriers without additional risk factors." (PMID 37929589, 2024).
breast cancer (4 papers, 2019 to 2024). A primary or metastatic malignant neoplasm involving the breast. "We then analyzed the expression levels of SIK2, phosphorylated MYL2 and phosphorylated MYLK in ovarian cancer cell lines (SKOV3, OVCAR8, OVCAR5, OVCAR3 and OVISE) and human breast cancer cell lines (MDA‐MB‐231 and Hs578 t)." (PMID 35278271, 2022).